MAN1B1 (mannosidase alpha class 1B member 1)
Description:
Involved in glycoprotein quality control targeting of misfolded glycoproteins for degradation. It primarily trims a single alpha-1,2-linked mannose residue from Man(9)GlcNAc(2) to produce Man(8)GlcNAc(2), but at high enzyme concentrations, as found in the ER quality control compartment (ERQC), it further trims the carbohydrates to Man(5-6)GlcNAc(2).
Synonyms: ERMan1; MANA-ER; MRT15; ERManI
Tractability: Small molecule: a structure with a bound ligand is known; a high-quality ligand is known; it belongs to a druggable protein family. Antibody: UniProt predicts a signal peptide or a membrane-spanning region. PROTAC: ubiquitination databases record sites on it; its protein half-life has been measured; a small molecule that binds it is known.
Target class: Enzyme; Hydrolase
Gene: Protein-coding gene on chromosome 9 (137,086,857 to 137,109,189, forward strand). Ensembl gene ENSG00000177239.
Subcellular location: Endoplasmic reticulum membrane
Subcellular location (Human Protein Atlas): Vesicles
Pathways (Reactome):
Disease: Defective MAN1B1 causes MRT15; Maturation of spike protein
Metabolism of proteins: ER Quality Control Compartment (ERQC)
Gene Ontology:
Molecular function: mannosyl-oligosaccharide 1,2-alpha-mannosidase activity; calcium ion binding
Biological process: endoplasmic reticulum mannose trimming; endoplasmic reticulum N-glycan trimming; ERAD pathway; oligosaccharide metabolic process; trimming of terminal mannose on C branch; viral protein processing; carbohydrate metabolic process; glycoprotein metabolic process
Cellular component: cytoplasmic vesicle; endoplasmic reticulum; endoplasmic reticulum membrane; endoplasmic reticulum quality control compartment; extracellular vesicle; membrane; Golgi apparatus
Genetic constraint (gnomAD): Loss-of-function variants: 68 observed, 73.39 expected, observed/expected ratio (o/e) 0.93, 90% interval 0.76 to 1.13. The synonymous counts are far from expectation, so gnomAD's model fits this gene poorly and the ratio says little. Missense variants: 973 observed, 917.99 expected, observed/expected ratio (o/e) 1.06, 90% interval 1 to 1.12. Synonymous variants: 453 observed, 380.28 expected, observed/expected ratio (o/e) 1.19, 90% interval 1.1 to 1.29.
Gene-disease validity (ClinGen):
ClinGen rates the evidence that MAN1B1 causes each of these diseases.
MAN1B1-congenital disorder of glycosylation (autosomal recessive): Definitive. MAN1B1-CDG is a form of congenital disorders of N-linked glycosylation characterized by intellectual disability, delayed motor development, hypotonia and truncal obesity.
Homologues: Orthologues: chimpanzee MAN1B1 (99% identical), macaque MAN1B1 (97% identical), guinea pig MAN1B1 (76% identical), mouse Man1b1 (74% identical), rat Man1b1 (71% identical), tropical clawed frog man1b1 (62% identical), zebrafish man1b1a (60% identical), zebrafish man1b1b (57% identical), Drosophila melanogaster alpha-Man-Ib (41% identical), Caenorhabditis elegans mans-4 (35% identical). Paralogues in human: MAN1A2 (29% identical), MAN1A1 (28% identical), MAN1C1 (28% identical), EDEM1 (24% identical), EDEM2 (22% identical), EDEM3 (21% identical).
Diseases named in the same sentence as MAN1B1 in open-access papers:
MAN1B1 is named in the same sentence as 32 diseases in open-access papers, as found by Europe PMC text mining. Sharing a sentence is not in itself a finding about the gene and the disease. The quoted sentences say what the papers report.
Intellectual disability (8 papers, 2013 to 2025). "Although seminal studies have genetically linked bi-allelic MAN1B1 mutations to intellectual disability (Rafiq syndrome), the underlying neurobiological mechanisms driving this phenotype remain largely unresolved." (PMID 40869158, 2025). "Our findings demonstrate that MAN1B1 deficiency disrupts neuronal and cortical development, and that loss-of-function mutations in MAN1B1 contribute to intellectual disability through impaired neurogenesis." (PMID 40869158, 2025). "Almost all of the patients who have been reported to have mutations in MAN1B1 exhibit intellectual disability, whereas the relationship between MAN1B and neurological has never been reported." (PMID 40869158, 2025). "MAN1B1 mutations were first linked to intellectual disability in 2011 with three distinct mutations identified across five consanguineous families." (PMID 40869158, 2025). "In this study, we identified a homozygous loss-of-function variant in MAN1B1 within a consanguineous family exhibiting intellectual disability (ID), thereby diagnosing the condition as Rafiq syndrome (RAFQS) through comprehensive genetic analysis." (PMID 40869158, 2025). "Among other mannosidases, human MAN1B1 deficiency has been linked to intellectual disability and MAN2B1 deficiency in humans causes a lysosomal storage disease known as alpha-mannosidosis." (PMID 35967980, 2022). "MAN1B1-CDG can be characterized by developmental delay/intellectual disability and an isolated increase of 3-sialo Trf linked to abnormal hybrid-type N-glycans." (PMID 34141584, 2021). "In the present study, we demonstrated that mutations in MAN1B1, a gene formerly linked to non-syndromic intellectual disability, cause CDG." (PMID 24348268, 2013). "Finally, MAN1B1-CDG is an autosomal recessive disease caused by the loss of ERMan I enzyme, and these patients also suffer from intellectual disability." (PMID 24609034, 2014). "Specifically, we systematically examined the role of MAN1B1 in cortical neurogenesis and neuronal morphogenesis, thereby providing mechanistic insights into the etiology of intellectual disability in RAFQS." (PMID 40869158, 2025). "Clinically, described MAN1B1-CDG individuals show intellectual disability (ID), developmental delay (DD), and facial dysmorphic features along with more or less frequent symptoms including hypotonia, truncal obesity and abnormal brain MRI." (PMID 34141584, 2021). "We described 7 patients with similar clinical features (developmental delay, intellectual disability, facial dysmorphism and obesity), defining MAN1B1-CDG as a syndrome." (PMID 24348268, 2013). "Overall, the clinical picture is mild, comprising not only intellectual disability, but also truncal obesity and facial dysmorphism, hence defining MAN1B1-CDG as a syndrome." (PMID 24348268, 2013). "MAN1B1-CDG is a CDG with nonspecific clinical symptoms such as intellectual deficiency and developmental delay." (PMID 34141584, 2021).
bladder cancer (4 papers, 2022 to 2025). "Studies suggest MAN1B1 as a potential cancer therapy target, promoting bladder cancer progression and linked to poor outcomes." (PMID 40264753, 2025). "The study demonstrated higher MAN1B1 expression in bladder cancer patients than in normal tissues from The Cancer Genome Atlas (TCGA) and Genotype Tissue Expression (GTEx) databases." (PMID 39559360, 2024). "Multifactorial analysis also confirmed that MAN1B1 expression was an independent prognostic factor for OS in bladder cancer patients." (PMID 39559360, 2024). "Thus, MAN1B1 is not only a novel biomarker for the diagnosis of BC, but also for assessing the prognosis and the degree of immune infiltration in bladder cancer patients." (PMID 39559360, 2024).
developmental delay (4 papers, 2021 to 2025). "This condition is caused by mutations in the MAN1B1 gene, which encodes a member of the glycosyl hydrolase family 47.The primary clinical features of Rafiq syndrome include intellectual and motor developmental delay, distinctive facial features, truncal obesity, and hypotonia." (PMID 41393301, 2025).
Obesity (4 papers, 2017 to 2025). Accumulation of substantial excess body fat. "MAN1B1-CDG is the only known CDG (type II) that is known to be associated with obesity in addition to slight facial dysmorphism and psychomotor retardation." (PMID 29112118, 2017).
Rafiq syndrome (4 papers, 2022 to 2025). Any autosomal recessive non-syndromic intellectual disability in which the cause of the disease is a mutation in the MAN1B1 gene. "Combined with gene sequencing, a compound heterozygous mutation was discovered in the MAN1B1 gene, diagnosed as Rafiq syndrome." (PMID 41393301, 2025). "CES was also ordered to help diagnose the patient's neurodevelopmental disorder, and a diagnosis of Rafiq syndrome (OMIM# 614202) was made by using the identified MAN1B1 variant." (PMID 38716412, 2024). "Rafiq syndrome (RAFQS) is a congenital disorder of glycosylation (CDG) that is caused by mutations in the MAN1B1 gene and characterized by impaired protein and lipid glycosylation." (PMID 36142510, 2022). "We feel that most dysmorphic features can be attributed to the MAN1B1 defect given the strong overlap with previously reported cases of Rafiq syndrome." (PMID 41393301, 2025). "Rafiq syndrome is a rare autosomal recessive genetic disorder, classified as a congenital disorder of glycosylation type II (MAN1B1-CDGII)." (PMID 41393301, 2025). "Rafiq syndrome (RAFQS) is a rare autosomal recessive disorder that is classified as a type II congenital disorder of glycosylation (CDG-II), and caused by MAN1B1 gene mutation." (PMID 40869158, 2025). "Notably, Rafiq syndrome (RAFQS), an autosomal recessive CDG-II subtype, is caused by bi-allelic mutations in the MAN1B1 gene." (PMID 40869158, 2025).
congenital disorder of glycosylation (3 papers, 2016 to 2023). Congenital disorder of glycosylation (CDG) is a fast growing group of inborn errors of metabolism characterized by defective activity of enzymes that participate in glycosylation (modification of proteins and other macromolecules by adding and processing of oligosaccharide side chains). "MAN1B1 deficiency is linked to Congenital Disorders of Glycosylation (CDG) that can manifest with intellectual and developmental disabilities." (PMID 36851531, 2023). "Nevertheless, the two patients were unresolved cases of congenital disorders of glycosylation (CDG) type II and were found to carry MAN1B1 mutations through exome sequencing." (PMID 27239352, 2016).
Truncal obesity (3 papers, 2013 to 2025). Obesity located preferentially in the trunk of the body as opposed to the extremities. "Subsequently, more and more patients with defective MAN1B1 were reported, showing individual variability in clinical phenotype, but most exhibited truncal obesity, joint hypermobility, a thin upper lip, short philtrum, and broad eyebrows." (PMID 40869158, 2025).
disorder of glycosylation (2 papers, 2013 to 2025). A disease that has its basis in the disruption of glycosylation. "In conclusion, we linked mutations in MAN1B1 to a Golgi glycosylation disorder." (PMID 24348268, 2013).
colon adenocarcinoma (1 paper, 2025). "Additionally, we showcased MAN1B1’s role in colon adenocarcinoma via in vitro assays, suggesting its suitability as a potential target for COAD therapeutics." (PMID 40264753, 2025).
congenital glycosylation type II disorder (1 paper, 2025). "from Belgium reported 7 patients carrying MAN1B1 gene mutations and classified these cases as congenital glycosylation type II disorder (CDG-II), suggesting that MAN1B1 gene mutations may be a potential pathogenic factor." (PMID 41393301, 2025).
congenital hypothyroidism (1 paper, 2025). A thyroid hormone deficiency present from birth. "We propose that the underlying etiology of congenital hypothyroidism (CH) in the proband is attributable to the combination of a DUOX2 gene mutation and ectopic thyroid, rather than a mutation in the MAN1B1 gene." (PMID 41393301, 2025).
Epileptic seizures (1 paper, 2021). "Epileptic seizures, including West syndrome, and coagulopathy resulting in strokes may be important complications of MAN1B1-CDG." (PMID 34831340, 2021).
Immunodeficiency (1 paper, 2026). Failure of the immune system to protect the body adequately from infection, due to the absence or insufficiency of some component process or substance. "Strikingly, exome sequencing also revealed variants in immunodeficiency-associated genes (IRAK4, USB1), autoinflammatory disorders (PSTPIP1) and unexpected candidates like ETV6, and MAN1B1 revealing previously unrecognised pathways in SLE development." (PMID 41930824, 2026).
liver cancer (1 paper, 2025). An epithelial or non-epithelial malignant neoplasm that arises from the liver. "A separate study indicated that miR-125b regulates liver cancer formation by targeting the product of the MAN1B1 gene." (PMID 40264753, 2025). "Hepatitis B virus facilitates liver cancer development by increasing MAN1B1 expression." (PMID 40264753, 2025).
lupus (1 paper, 2023). "A genetic diagnosis involving a gene never associated with lupus (MAN1B1, ETV6) was identified in 2 patients, explaining part of the phenotype but not the lupus." (PMID 37848930, 2023).
cancer (4 papers, 2013 to 2025). A tumor composed of atypical neoplastic, often pleomorphic cells that invade other tissues. "On the other hand, MAN1B1 exhibited the opposite behavior, showing increased expression in cancer compared to healthy tissues, with the expression levels rising as the disease progressed." (PMID 40430030, 2025). "Secondly, in order to investigate the possible connection between MAN1B1 and the cancer-related immune microenvironment in BC, more investigations were needed." (PMID 36016584, 2022). "In this study, we first performed a pan-cancer analysis and observed that MAN1B1 expression was distinctly increased in most types of tumors, which was consistent with previous findings in BC." (PMID 36016584, 2022). "In human cancers, MAN1B1 expressions were shown to be generally higher in tumors than in normal specimens." (PMID 36016584, 2022). "Based on TCGA datasets, we investigate the level of MAN1B1 expression in each of the many cancer types." (PMID 36016584, 2022). "The Cancer Genome Atlas (TCGA) and Genotype-Tissue Expression (GTEx) databases provided the raw information that was used to analyze the expression of MAN1B1 in tumor patients." (PMID 36016584, 2022). "MAN1B1 was identified as a harmful predictor, highly expressed in most malignant tumors." (PMID 40264753, 2025).
tumor (4 papers, 2022 to 2025). "The correlation between MAN1B1 expression and tumor immune infiltration was explored via single-sample gene set enrichment analysis (ssGSEA)." (PMID 36016584, 2022). "Mutations in the FGFR3 gene are associated with low PD-L1 expression in BC, high expression of MAN1B1 is related to poor prognosis, high expression of COL6A1 in tumor cells promotes tumor growth and metastasis, and high expression of NXPH4 is associated with poor prognosis in BC." (PMID 39559360, 2024). "Contrastingly, MAN1B1 showed a negative correlation with all the other mannosidases, further supporting its distinct expression pattern and denoting a different glycophenotype within the tumor microenvironment." (PMID 40430030, 2025).
MAN1B1 also shares sentences with these, for which no sentence is quoted: autosomal-recessive intellectual disability (3 papers); hepatocellular carcinoma (2); alpha-mannosidosis (1); and developmental disabilities (1); Ehlers-Danlos syndrome (1); End Stage Liver Disease (1); glioma (1); infection (1); liver disease (1); liver dysfunction (1); lysosomal storage disease (1); neurodevelopmental disorder (1); neurological disorders (1); Stroke (1); West syndrome (1).